SUN1 (Sad1 and UNC84 domain containing 1)
Diseases named in the same sentence as SUN1 in open-access papers (continued):
Sharing a sentence is not in itself a finding about the gene and the disease.
infection (6 papers, 2017 to 2025). The state of being infected such as from the introduction of a foreign agent such as serum, vaccine, antigenic substance or organism. "In brief, RGG-expressing ECs were exposed to long-term inflammation (TNFα [10ng/mL]; 6 days) to induce senescence, followed by exogenous Sun1-FLAG infection." (PMID 40777343, 2025). "Like SUN1, SUN2 poorly affected the infection of HIV-1 bearing the capsid mutation G208R, which is in agreement with our previous results suggesting that capsid mutations overcome the HIV-1 restriction imposed by overexpression of SUN222." (PMID 34580332, 2021). "One possibility is that the interaction between the N-terminal domain of SUN1 or SUN2 with the pre-integration complex negatively affects infection by changing the localization of the core in the nuclear compartment." (PMID 34580332, 2021). "On the other hand, SUN1 is dispensable in the infection of ZIKV and DENV2." (PMID 38177122, 2024). "Overall this is in agreement with the hypothesis that the N-terminal domain of SUN1/2 is interacting with capsid during infection and that this interaction is important for restriction." (PMID 34580332, 2021). "These suggested different roles of SUN1 protein in two pathogens with different infection modes." (PMID 34589077, 2021). "In agreement with the inability of SUN1 and SUN2 to block infection of HIV-1 viruses bearing the capsid changes G208R or P207S, we saw that SUN1 and SUN2 showed decreased binding to capsid bearing G208R or P207S changes when compared to wild type." (PMID 34580332, 2021). "The infectivity of HIVac-1 GFP LV was severely reduced in THP-1 control cells as well as in THP-1 SUN1 or SUN2 knockout cell clones, and CS treatment rescued infectivity in all cases to infection levels of the wild-type LV." (PMID 28747499, 2017). "We then tested infection by the transmitted founder (T/F) viruses RHPA, SUMA, WITO, THRO, and ZM247: SUMA, WITO, and THRO infectivities were all reduced by ∼6- to ∼10-fold by SUN1, whereas RHPA and ZM247 were largely unaffected." (PMID 28747499, 2017). "We propose here that the INM components SUN1 and SUN2, two members of the linker of nucleoskeleton and cytoskeleton (LINC) complex, may interact with incoming HIV-1 replication complexes and affect key steps of infection." (PMID 28747499, 2017).
myopathies (2 papers, 2014 to 2017). "Screening of the SUN1 and SUN2 genes in a large cohort of patients with EDMD and phenotypically related myopathies identified SUN1 and/or SUN2 variants in several patients." (PMID 25210889, 2014). "We have identified a total of 11 SUN1 and 7 SUN2 rare, non-synonymous variants in our cohort of EDMD and related myopathy patients." (PMID 25210889, 2014). "Using a candidate approach, we have identified putative disease-causing variants in the SUN1 and SUN2 genes, also encoding LINC complex components, in patients with EDMD and related myopathies." (PMID 25210889, 2014). "Whether the functions of SUN1 and SUN2 in the DDR are connected with their roles in myopathies and other laminopathies is currently unresolved." (PMID 28747499, 2017). "We identified 5 rare, non-synonymous SUN1 and/or SUN2 variants in 3 individuals who lacked mutations in other genes but had EDMD or related myopathy phenotypes." (PMID 25210889, 2014).
cardiac disease (1 paper, 2014). "In other cases, the additional presence of a SUN1/SUN2 mutation was associated with more severe cardiac disease." (PMID 25210889, 2014).
cardiovascular disease (1 paper, 2023). "Our finding that SUN1 regulates endothelial cell junction integrity and blood vessel sprouting has implications for diseases associated with aging, as vascular defects underlie most cardiovascular disease." (PMID 36989130, 2023).
psychiatric disorder (1 paper, 2025). A disorder characterized by behavioral and/or psychological abnormalities, often accompanied by physical symptoms. "Mutations in SUN1 disrupt neuronal migration, which is linked to neurological and psychiatric disorders, including SZ." (PMID 41333685, 2025).
SUN1 also shares sentences with these, for which no sentence is quoted: autism spectrum disorder (1 paper); Duchenne muscular dystrophy (1); glioma (1); liver fibrosis (1); melanoma (1); open-angle glaucoma (1); schizophrenia (1); Sepsis (1); virus infection (1).